PTX3 (pentraxin 3)
Diseases named in the same sentence as PTX3 in open-access papers (continued):
Sharing a sentence is not in itself a finding about the gene and the disease.
tumor (continued). "In contrast, the shINHA hypoxia tumors showed increases in proteins including ADAMTS-1 (1.6 times) and Pentraxin-3 (1.3 times), indicating an anti- angiogenic profile in shINHA tumor cells as both have been demonstrated to be anti-angiogenic." (PMID 35654828, 2022). "The transcription factor CCAAT/enhancer binding protein delta (CEBPD) activates the PTX3 gene in stromal cells, contributing to cancer and chemoresistant tumour progression." (PMID 35090088, 2022). "We proved the regulatory role of PTX3 in the migration and polarization of macrophages in the tumor microenvironment of GBM." (PMID 35855654, 2022). "Tumor patients with high PTX3 expression seem to confer a worse prognosis and their immunotherapy requires careful and wise choices against different cancers." (PMID 36139597, 2022). "PD-L1+ PCs showed a decrease in PD-1+ lymphocytes and tumor-infiltrating macrophages (mainly M2 subpopulation), while PTX3 expression inversely correlated to the number of PD-L1+ PC cells." (PMID 34831389, 2021). "Accordingly, a reduced rate of MM cell proliferation paralleled by a reduced FGFR1 activation occurred in vivo in both endothelial and tumor cells when PTX3 was overexpressed and accumulated in the extracellular matrix of grafted tumors." (PMID 34066669, 2021). "Several studies identified that PTX3 plays a predominate role in infection, inflammation, immunity and tumor." (PMID 33746606, 2021). "SHH MB subgroup has increased expression of inflammation-related genes (CD14, PTX3, CD4, CD163, CSF1R, and TGFB2) and significantly higher infiltration of tumour-associated fibroblasts than Grp3 MB and Grp4 MB." (PMID 34195095, 2021). "A dramatic in vivo decrease has been reported in tumorigenic potential and angiogenic activity in tumor cells that overexpress PTX3." (PMID 34048179, 2021). "In another study, the knockdown of pentraxin 3 (PTX3) activated the proliferation of BC cells and enhanced the metabolism of tumor cells." (PMID 34266411, 2021). "In preclinical models, PTX3 functions as an extrinsic oncosuppressor gene, reducing complement-driven macrophage-mediated tumour promotion and suggesting the potential role as an immunosuppressive agent through the establishment of cellular senescence." (PMID 34572075, 2021). "This is similar to our findings, as we found that PTX3 was low-expressed in tumor cells by protein expression." (PMID 34745947, 2021). "In keeping with these findings, we have recently reported a significant reduction of tumor vascularization of subcutaneous KMS-11 xenografts in mice treated with the PTX3-derived small molecule NSC12." (PMID 34066669, 2021). "Further analysis showed that the expression level of PTX3 was significantly correlated with the degree of tumor differentiation." (PMID 33952272, 2021). "Studies in tumors showed that PTX3 promoted cell migration and invasion, and its expression level was related to the progression of different tumor types in humans." (PMID 33952272, 2021). "Recently, a novel therapeutic strategy for cancers is raised by virtue of overexpression of PTX3 which inhibits fibroblast growth factor-2 (FGF2) dependent tumor growth." (PMID 33746606, 2021). "The colony forming assay also supported JUN can affect tumor viability through affecting PTX3 expression." (PMID 32984316, 2020). "In some cases PTX3 acts as tumor suppressor, inhibiting the proliferation and angiogenesis of FGF2-mediated tumor cells, as well as the epithelial-to-mesenchymal transition (EMT) and its metastatic potential." (PMID 32345771, 2020). "Pentraxin 3 (PTX3), an inflammatory marker and a pattern recognition receptor, plays an important role in promoting the progress of tumor and inflammatory diseases." (PMID 31957804, 2020). "Intriguingly, after nephrectomy PTX3 levels significantly lowered, thus strengthening the relationship between intra-tumor PTX3 production and PTX3 serum levels." (PMID 32345771, 2020).
tumor (continued). "In this frame, PTX3 has been shown to act as an oncosuppressor in different FGF-dependent tumors by inhibiting tumor growth, neovascularization, and metastatic dissemination." (PMID 32630309, 2020). "It was found that the expression of PTX3 in low-grade and high-grade tumors was different and positively correlated with tumor grade and severity." (PMID 31957804, 2020). "The CCK8 assay indicate that increased JUN expression can promote tumor cells proliferation, but by silencing PTX3 expression can reverse that process." (PMID 32984316, 2020). "Previous studies confirmed that elevated PTX3 level in tumor tissue as a biomarker of poor survival outcome." (PMID 32984316, 2020). "The aim of our study was to investigate the role of PTX3 as possible modulator of Complement activation in the development of this neoplasia." (PMID 33110136, 2020). "PTX3 inhibit tumor progression via combining to receptor of fibroblast growth factor-8b (FGF8b) and metastasis by activating the EMT process." (PMID 33013829, 2020). "PTX3 has been confirmed relate to tumor migration, growth, sensitivity to radiotherapy, but its relationship with autophagy in GBM is remained unclear." (PMID 32984316, 2020). "Then, we analyzed the tissue expression of PTX3 in tumor tissues of 30 consecutive patients who underwent radical nephrectomy for ccRCC." (PMID 32345771, 2020). "Deglycosylased PTX3 observed suppress tumor migration via inactivating the PI3K/AKT and the NF-κB signaling pathway." (PMID 33013829, 2020). "Of note, Fcγ receptor expression on NK cells modulates tumor response to immunotherapy, and PTX3 can exert its function in human immunity by interacting with this receptor." (PMID 33013829, 2020). "PTX3 also inhibits cell proliferation and tumor metastasis by modulating the expression of protein related to the G2/M phase cell-cycle in cervical cancer." (PMID 33013829, 2020). "Otherwise, it has been documented that in the model of epithelial carcinogenesis, cytokines TNF-α, was suggestively greater in PTX3-/- tumor homogenates compare to PTX3+/+17." (PMID 32194791, 2020). "Our data indicate that loss of FAK in CAFs from FSPCre−;FAKfl/fl mice increases Ccl6, Ccl11, Ccl12 and pentraxin-3 expression with an enhancement in malignant cell glycolysis and tumour growth." (PMID 32157087, 2020). "By silencing PTX3 expression can impair tumor cells colony-forming and proliferation ability in vitro." (PMID 32984316, 2020). "As a novel multifaceted player in cancer, Pentraxin3(PTX3) was recognized to be a possible factor related with tumor development." (PMID 32194791, 2020). "Because of PTX3 overexpression, tumor samples were also characterized by a significant reduction of CD4+ and CD8+ lymphocyte, mast cell and CD68+ macrophage pro-inflammatory populations." (PMID 31533326, 2019). "Transgenic PTX3 overexpression by tumor cells impairs the activation of the FGF/FGF receptor (FGFR) system in FGF-driven tumor cell lines, affecting tumor growth and metastasis in different models of melanoma, prostate, and mammary carcinomas." (PMID 31533326, 2019). "Pentraxin-related protein 3 (PTX3) has been identified as a tumor suppressor negatively regulating complement-mediated inflammation." (PMID 31134065, 2019). "Long pentraxin 3 (PTX3) is produced by various cell types and is correlated with tumor progression in various tumor types." (PMID 31334115, 2019). "In humans, PTX3 expression is increased in different cancers, while in mice FH recruitment by PTX3 to C3b deposited on tumor cells has been shown to restrict the development of local inflammation." (PMID 31428091, 2019). "In this study, starting from database analysis and immunehistochemical data on tumor samples from BC patients, we’ve shown that PTX3 downmodulation follows the progression of BC tumors from low-grade to high-grade/muscle invasive BC." (PMID 31480336, 2019).
tumor (continued). "IHC on tumor specimens confirmed a strong positivity for PTX3 in PTX3-MC17-51 samples and in MC17-51 tumors grown in TgN(Tie2-hPTX3) mice when compared to the corresponding controls." (PMID 31533326, 2019). "In agreement with the anti-tumor activity exerted by both tumor cell- or stroma-derived PTX3, tumor neovascularization was significantly reduced in the presence of PTX3." (PMID 31533326, 2019). "PTX3 is involved in different aspects of tumor progression, including tumor cell proliferation, angiogenesis, metastatic dissemination, and cancer immune modulation." (PMID 31480336, 2019). "PTX3 can be produced by both tumor and stromal cells, making the study of its impact on the tumor microenvironment particularly complex." (PMID 31480336, 2019). "PTX3 knockout goes along with increased C3 deposition in neoplastic tissues that correlates with an increased tumor progression." (PMID 31533326, 2019). "PTX3 promotes cell migration and invasion in several cancers, and the expression of PTX3 correlates with tumor progression in various human tumor types." (PMID 31334115, 2019). "PTX3 expression was correlated with advanced stage, larger tumor size, presence of intra-hepatic metastases, portal vein tumor thrombosis and liver cirrhosis." (PMID 31019517, 2019). "Similar results were obtained in a zebrafish/tumor xenograft model where the angiogenic response to FGF2-overexpressing tumor cells was strongly impaired by the co-injection of PTX3 or ARPCA." (PMID 30349543, 2018). "PTX3 has recently been shown to contribute in regulation of tumor growth, which was attributed to its capacity in control of tumor promoting inflammation through coordination with complement regulator fH." (PMID 30619374, 2018). "PTX3 is considered a tumor suppressor gene that plays a role in tumor-promoting inflammation in cancer." (PMID 28327132, 2017). "In the recent report, extrinsically derived PTX3 acts as an oncosuppressor by regulating complement-dependent tumor-promoting inflammation." (PMID 28489600, 2017). "We found that oleate dramatically enhanced tumor-endothelial interactions by inducing the autocrine production of PTX3." (PMID 28489600, 2017). "To determine the effects of PTX3 on oleate-induced metastasis in vivo, we investigated the distant dissemination (e.g., pulmonary colonization) of tumor cells using tail-vein injections in an animal model." (PMID 28489600, 2017). "The enhancement of binding between tumor and endothelial cells was observed in oleate-treated cells but not in the depletion and neutralization of PTX3 with siPTX3 and anti-PTX3 antibodies, respectively." (PMID 28489600, 2017). "In an in vivo assay, the metastatic seeding of the lungs by oleate-primed tumor cells was inhibited by the depletion of PTX3." (PMID 28489600, 2017). "On the other hand, for the first time, we found that the oleate-primed metastasis was regulated by the expression of PTX3 in tumor cells." (PMID 28489600, 2017). "PTX3 acts as an extrinsic oncosuppressor by regulating complement-dependent tumor-promoting inflammation." (PMID 28489600, 2017). "On the whole, certain observations point toward a protective role of PTX3 against CD and tumor, acting through a better tuning of inflammatory response." (PMID 28536575, 2017). "Strategies focused on down-regulating TMEM158, Mybl1, IL32, ETS1 and PTX3 should be considered to determine their effect on TNBC tumor progression." (PMID 28966727, 2017). "In this study, we found that oleate-induced PTX3 enhanced vimentin expression to promote tumor invasion." (PMID 28489600, 2017). "Accordingly, injection of TRAMP-C2 cells in transgenic male mice overexpressing PTX3 under the control of the endothelial Tie2-promoter results in a significant inhibition of the growth and vascularization of the tumor graft." (PMID 29137286, 2017). "On the contrary, PTX3 overexpression inhibited tumor angiogenesis and metastasis in heterotopic and orthotopic FGF-dependent transgenic mice models." (PMID 27377307, 2016).
tumor (continued). "Statistical analyses suggested that PTX3 expression strongly correlated with tumor grade (P < 0.011) and tumor differentiation (P < 0.019), whereas the expression of PTX3 was not significantly different between age groups." (PMID 27377307, 2016). "Knockdown of PTX3 by lentiviral vector-mediated PTX3 shRNA suppressed tumor invasion by inhibiting expression of Akt, NF-κB, proliferating cell nuclear antigen, and MMP-911." (PMID 27377307, 2016). "In the current study, we further revealed involvement of PTX3 in the tumor microenvironment in promoting cancer metastasis, invasion and stemness." (PMID 26124179, 2015). "The tail-vein injection animal model revealed that depletion of PTX3 decreased EGF-primed tumor cell metastatic seeding of the lungs." (PMID 25797258, 2015). "We further studied the effect of PTX3 on the endothelial transmigration of tumor cells in a three-dimensional in vitro model." (PMID 25797258, 2015). "Consistent with what was observed in the transendothelial invasion assay, depletion of PTX3 inhibited metastatic seeding of EGF-primed tumor cells in the lungs." (PMID 25797258, 2015). "The identification of PTX3 provided a new insight in the interaction between host and tumor and the RI37 peptide showed a great opportunity to largely reduce the risk of invasion and metastasis of cancer and drug-resistant cancers." (PMID 26124179, 2015). "In particular, PTX3 inhibits the angiogenic and tumorigenic activity of androgen-regulated tumor cells in which testosterone activates a FGF8b-dependent autocrine/paracrine loop of stimulation." (PMID 25912421, 2015). "Recent studies demonstrated that FH binds to pentraxin 3 (PTX3) in the tumor microenvironment, thus preventing local complement overactivation and generation of pro-tumorigenic C5a." (PMID 26074922, 2015). "We previously demonstrated that CEBPD-induced PTX3 in macrophages promotes cancer progression by preventing the macrophage-mediated phagocytosis of tumor cells." (PMID 26124179, 2015). "A panel of selected representative pro-inflammatory genes (RAGE and P2X7R, COX2, NOS2 and, PTX3) were analyzed, comparing tumor, peritumor and host normal tissues." (PMID 21489226, 2011). "PTX3 has been reported to promote cell migration and invasion in various tumor models." (PMID 41373493, 2025). "Prior studies have suggested that PTX3 may reflect a more aggressive tumor phenotype in other cancers, indicating that it could also have prognostic relevance." (PMID 41373493, 2025). "Upregulated mRNA levels of PTX3 were observed in tumor tissues across these datasets." (PMID 40656950, 2025). "PTX3 expression showed a strong correlation with immune cell infiltration, particularly macrophages, neutrophils, T cells, and natural killer cells, suggesting a role in modulating the tumor microenvironment." (PMID 40656950, 2025). "Overall, PTX3 appears to promote tumor progression in various models." (PMID 41373493, 2025). "Investigating the dynamic changes in PTX3 within the tumor microenvironment may help uncover new insights." (PMID 41479916, 2025). "Beyond CRC, a study also highlighted the tumor-suppressive role of PTX3 in ESCC." (PMID 41479916, 2025). "In our study, however, there was a low co-localization of the CD68 and PTX3 in the tumor microenvironment, suggesting that PTX3 was mainly produced by tumoral cells, other immune cells, or stromal cells rather than the CD68-positive macrophages that were highly infiltrating the tumors." (PMID 41373493, 2025). "PTX3 tissue expression in PTC may be highly localized within the tumor microenvironment, particularly in specific cell populations or stromal areas." (PMID 41373493, 2025). "Numerous studies have highlighted the role of PTX3 promoter methylation in tumor progression, suggesting that drugs targeting DNA methylation could help mitigate tumor progression, particularly in cancers of the digestive system." (PMID 41479916, 2025).
tumor (continued). "Additionally, the tumor suppressor Menin upregulates PTX3 expression by enhancing H3K4me3 accumulation at its promoter in the decidua during normal pregnancy." (PMID 41479916, 2025). "Additionally, elderly patients are at an increased risk of blood–brain barrier impairment, which heightens the likelihood of PTX3 derived from peripheral blood infiltrating the tumor microenvironment." (PMID 40656950, 2025). "The positive correlation between PTX3 and macrophage infiltration suggests that PTX3 may promote the recruitment or activation of these immune cells, thereby enhancing anti-tumor immunity." (PMID 40656950, 2025). "These opposing findings imply that the role of PTX3 may depend on the cancer type or the state of the tumor microenvironment." (PMID 38243273, 2024). "PTX3 is a humoral innate immune molecule produced by macrophages and mesenchymal cells, which plays a role of extrinsic oncosuppressor of cancer by regulating complement-dependent tumor-promoting inflammation." (PMID 39575252, 2024). "To assess this hypothesis, we examined whether blockade of PTX3 still affects MC38 tumor growth in immunodeficient mice." (PMID 38243273, 2024). "Targeting PTX3 could provide a novel approach to mitigating tumor progression and improving patient outcomes, especially in cases where conventional therapies may be less effective against aggressive, poorly differentiated cancer cells." (PMID 39594709, 2024). "To assess whether PTX3 is involved in MEF-mediated tumor growth, we coinjected Ptx3 knockdown MEFs (shPtx3#915, shPtx3#916) or control MEFs (shVoid) and monitored MC38 tumor growth in vivo." (PMID 38243273, 2024). "The authors of some studies have demonstrated the tumor-suppressive effects of the PTX3 protein." (PMID 39594709, 2024). "It has already been established that the immune system plays a role in tumour initiation and progression in which the inflammatory marker pentraxin 3 (PTX3) might be involved, presenting a variety of functions in different cancers." (PMID 38542446, 2024). "Furthermore, increased expression of PTX3 in PCa was found to be indispensable for cancer cell migration and correlated with tumour metastasis." (PMID 39187920, 2024). "Additionally, serum PTX3 levels remained markedly higher than those in healthy control subjects, even after tumor removal." (PMID 39686456, 2024). "These contradictory findings imply that PTX3 may play a dual role in tumorigenesis, possibly depending on the types of malignancies, or on the cells producing it within the tumour microenvironment." (PMID 39187920, 2024). "In BC, patients with NMBIC have been found to have higher PTX3 expression in tumour tissues compared to patients with MBIC, suggesting that the overexpression of PTX3 could be associated with a better prognosis in BC patients." (PMID 38542446, 2024). "Blockade of PTX3 significantly reduced stromal cell-mediated tumor development." (PMID 38243273, 2024). "Our analysis revealed a significant association between worse prognosis in malignant tumors and high PTX3 levels, both in tumor tissue and serum, suggesting that PTX3 could serve as a prognostic biomarker when measured in these biological samples." (PMID 39594709, 2024). "Based on several reports demonstrating the role of PTX3 in regulating inflammation, we speculated that PTX3 contributes to tumor progression by mediating tumor immunity." (PMID 38243273, 2024). "To gain insight into how PTX3 contributes to stroma-mediated tumor growth, we initially explored whether PTX3 can directly promote the proliferation of cancer cells." (PMID 38243273, 2024). "To determine whether PTX3 induces desmoid tumor cell proliferation via STAT6 activation, we combined recombinant PTX3 protein treatment with AS1517499." (PMID 37377751, 2023). "However, even though the mechanisms by which PTX3 exerts its anti-tumor activity are at least partially known, the mechanisms by which PTX3 exerts its tumorigenic activity have still to be revealed." (PMID 37749607, 2023).